ATM (ATM serine/threonine kinase)
Diseases named in the same sentence as ATM in open-access papers (continued):
Sharing a sentence is not in itself a finding about the gene and the disease.
lymphoma (continued). "Notably, loss of ATM preferentially affects NHEJ and predisposes patients primarily to lymphomas." (PMID 27304073, 2016). "In lymphoma cells, it has been suggested that PIM2 expression is induced by ATM activation after detection of DNA strand breaks." (PMID 38203596, 2023). "Interestingly, ATM deficiency did not lead to ROS accumulation in lymphoma environment." (PMID 33273545, 2020). "Staining of ATM, SIRT1 and SIRT3 in lymphoma patients demonstrated a variation in their degree of expression suggesting a differential requirement of these critical markers during tumor development." (PMID 33273545, 2020). "miR-18a inhibited ATM-mediated DDR and increased the virus proliferation, increasing the growth of lymphomas and indicating the oncogenic effect of EBV is dependent on the host microenvironment." (PMID 30594162, 2018). "ATM −/− mice were not included in the aging studies because these mice die at ~6 mo, typically from lymphoma." (PMID 37787989, 2023). "Mice with ATM D2880A/N2885K mutations corresponding to D2870A/N2875K in humans developed blood and lymphoid cancers faster than mice with complete absence of ATM." (PMID 34771661, 2021). "Collectively, B-PAC-1 stimulates PCD in primary lymphomas regardless of ATM status and this was partially reverted by Zn addition." (PMID 26658105, 2016). "Here we report that heterozygous loss of Bcl11b (Bcl11b(+/-)) unexpectedly reduced lethal thymic lymphoma in ATM(-/-) mice by suppressing lymphoma progression, but not initiation." (PMID 26219558, 2015). "As well, caspase-2 loss enhanced lymphoma formation in mice bearing the Eμ-myc transgene or lacking ATM (ataxia telangiectasia mutated)." (PMID 27919034, 2014). "Overall, this suggests no major disruption of signalling by ATR and ATM in Eμ-Myc Rel−/− lymphomas but that specific targets exhibit changes in phosphorylation that could impact on the phenotype of these cells." (PMID 36240066, 2022). "Insights from this work will be relevant to cells carrying mutations in the ATM gene, which are present in many cancers (e.g., in about 45% of lymphomas), wherein lack of ATM may promote invasion or intra- and extravasation of tumor cells during the early steps of metastasis." (PMID 35721517, 2022).
gastric cancer (91 papers, 2009 to 2026). A primary or metastatic malignant neoplasm involving the stomach. "Synthetic lethality between ATR inhibition and ATM deficiency has also been shown previously in gastric cancer cells and other tumors, as cells with loss of ATM rely only on ATR for orchestrating DDR." (PMID 41614897, 2026). "miR-181a-5p downregulates ATM, whose pathogenic variants interact with H. pylori infection to increase additively the risk of gastric cancer." (PMID 40045434, 2025). "These pathways include Homologous recombination, basal transcription factors, DNA double-strand break repair and cellular responses via ATM (ataxia-telangiectasia mutated), and gastric cancer network pathways." (PMID 38662056, 2024). "For other malignancies, such as gastric-cancer and renal cell carcinoma, similar relations between ATM mutations and response to PARP inhibition have been reported." (PMID 38642130, 2024). "A recently published combination study of ceralasertib and immune-checkpoint blockade (ICB) with durvalumab in advanced gastric cancer found a benefit in those patients with ATM loss or HR deficiency and found that responders had changes in their immune TME." (PMID 37934611, 2024). "Specifically, P/LP variants in the ATM gene are associated with gastric and thyroid cancers, and risk estimates have also been described; for gastric cancer, several studies associated ATM mutations with OR (odds ratio) ranging from 2.97 to 4.74." (PMID 38890714, 2024). "The results showed that RAD51D was not a risk factor for gastric cancer, but other BRCA1, BRCA2, and ATM genes from the homologous recombination pathway are risk factors for gastric cancer." (PMID 39206620, 2024). "Familial early-onset gastric cancer with high penetrance is an unusual presentation for ATM variants." (PMID 37509701, 2023). "The frequency of deleterious ATM variants in patients with gastric cancer was thereby demonstrated to be significantly higher than in controls." (PMID 37509701, 2023). "As in other cancer susceptibility genes, the heterozygous germline ATM variants identified in a cohort of patients with gastric cancer were truncating." (PMID 37509701, 2023). "The frequency of gastric cancer in the family appears to be unusual for kindred individuals with ATM mutation carriers." (PMID 37509701, 2023). "We describe a family presenting early-onset gastric cancer and harboring a heterozygous pathogenic ATM variant." (PMID 37509701, 2023). "Pathogenic variants in several other genes can cause gastric cancer susceptibility, usually alongside with risks for other neoplasms, including the ATM gene (MIM *607585)." (PMID 37509701, 2023). "We herein report on a family ascertained for hereditary gastric cancer, with a heterozygous pathogenic truncating variant in ATM." (PMID 37509701, 2023). "Estimates of specific cancer risks are emerging, and for gastric cancer, the reported risk conferred by heterozygous ATM PVs is up to three times higher than in the general population (odds ratio (OR) of 2.97; 95% CI, 1.66–5.31)." (PMID 37509701, 2023). "In their study on gastric cancer they identified sensitivity for veliparib in case of ATM loss-of-function mutations of ATM9." (PMID 33712636, 2021). "Huang et al16 found that 2.7% of patients with gastric cancer sequenced via The Cancer Genome Atlas harbored an ATM variant, similar to the findings of the current study and significantly higher than in control populations." (PMID 34251444, 2021). "Of note, four gene-disease associations, i.e., ATM-gastric cancer, CHEK2-gastric cancer, CHEK2-kidney cancer, and CHEK2-thyroid cancer, were not identified in any of the six resources but were verified by the NLP-aided literature review." (PMID 33959510, 2021).
gastric cancer (continued). "On the other hand, high ATM mRNA levels were associated with better overall survival but low ATM mRNA levels implied poorer overall survival from gastric cancer (p = 0.018, hazard ratio = 0.68)." (PMID 34503060, 2021). "A recent study reported that ATM carriers were significantly associated with lower protein expression in five cancer types, including gastric cancer." (PMID 33959510, 2021). "They found a new gastric cancer association with loss-of-function mutations in ATM (OR = 4.74, p = 8.0 × 10-12)." (PMID 33959510, 2021). "This trial as well as others are additionally examining the effects of AZD6738 alone or in combination with PARP inhibitor to treat a number of solid tumors, including ATM deficient gastric cancer (NCT03682289, NCT03462342)." (PMID 33498525, 2021). "Response rates to PARPis in ATM-deficient tumor cell lines were seen in chronic lymphocytic leukemia, gastric cancer, and mantle cell lymphoma." (PMID 33233320, 2020). "We have previously shown that loss-of-function mutations in ATM confer high risk of gastric cancer in the Icelandic population." (PMID 30194396, 2018). "ATM–deficient mantle-cell lymphoma and gastric cancer cells respond better to Olaparib than the ATM-proficient cells." (PMID 27613518, 2016). "Using a TCGA dataset of 335 gastric cancer patients, we estimated the prevalence of ATM germline mutations and identified 9 deleterious mutations including 6 truncating mutations." (PMID 26506520, 2015). "Our results are consistent with the reports from studies on tissue samples from pancreatic and gastric cancer patients, which showed that loss of ATM expression was associated with tumor progression." (PMID 26275218, 2015). "The frequency of ATM deleterious mutations was significantly higher in the gastric cancer patients than that in general population (9/335 for TCGA gastric cancer data vs. 6/2054 for 1000 genomes data; odds ratio = 9.41;the Fisher exact test, p = 0.0000435)." (PMID 26506520, 2015). "Future work is needed to evaluate ATM mutations for risk assessment and therapy development in gastric cancer." (PMID 26506520, 2015). "In our study, we found a frameshift mutation (p.Y1203fs) and a missense mutation (p.N1223S) in ATM in a Chinese gastric cancer family." (PMID 26506520, 2015). "Our observation of a truncating mutation of ATM in a Chinese family of gastric cancer history, as well as the prevalence of deleterious ATM variants in patients of different ethnic origins are consistent with their results." (PMID 26506520, 2015). "Further evaluation of ATM mutations in hereditary gastric cancer will facilitate genetic testing and risk assessment." (PMID 26506520, 2015). "The discovery of two rare ATM mutations (one is likely to be deleterious) in the family promoted us to investigate the frequency of deleterious ATM germline mutations in gastric cancer patients." (PMID 26506520, 2015). "In this study, we discovered two germline ATM mutations (p.Y1203fs and p.N1223S) in a Chinese family with a history of gastric cancer by screening 83 cancer susceptibility genes." (PMID 26506520, 2015). "The frequency of deleterious ATM mutations in gastric cancer patients is significantly higher than that in general population (p=0.0000435), suggesting an association of ATM mutations with gastric cancer predisposition." (PMID 26506520, 2015). "Studies in tumor samples from pancreatic, breast and gastric cancer patients revealed a correlation between loss of ATM expression, disease progression and poor prognosis, indicating its tumor suppressing nature." (PMID 26275218, 2015). "Nevertheless, the discovery of deleterious ATM mutations raises the question of the predisposition role of ATM in gastric cancer." (PMID 26506520, 2015). "Using a published exome sequencing dataset, we found deleterious germline mutations of ATM in 2.7% of 335 gastric cancer patients of different ethnic origins." (PMID 26506520, 2015).
gastric cancer (continued). "These suggest the ATM gene intron mutation targeted by microsatellite instability is associated with ATM protein loss in a subset of human gastric cancer." (PMID 24324828, 2013). "Ten human gastric cancer cell lines were studied for the ATM gene mutation at introns, RT-PCR, direct sequencing, and immunohistochemistry." (PMID 24324828, 2013). "ATM has also been implicated in breast, lung, head and neck carcinoma, and is associated with a poor prognosis in adult patients with advanced gastric cancer." (PMID 19284625, 2009). "However, WES analyses found some evidence of high HRD scores in tumours from ATM germline P/LP variant carriers (see Tumour analyses of gastric carcinomas of patients carrying P/LP variants, above)." (PMID 40446793, 2025). "The population frequency of ATM PV carriers and of sporadic gastric cancer cases, the moderate and age-dependent penetrance of the cancer susceptibility phenotype for ATM, and the rarity of the identified variant pose significant challenges to genotype–phenotype correlation attempts." (PMID 37509701, 2023). "We cannot exclude that the nonsense ATM variant identified in this family might be correlated with a specifically higher gastric cancer risk, but further research is needed to provide an assertion." (PMID 37509701, 2023). "One patient carrying an ATM pathogenic mutation with BC also developed gastric cancer." (PMID 33919281, 2021). "Six patients 50 years or younger had ATM LP/P variants (2 with gastric cancer, 1 with GEJ cancer, and 3 with esophageal cancer), of whom family gastric cancer history was positive in all 3 patients with available histories (2 with gastric cancer and 1 with GEJ cancer)." (PMID 34251444, 2021). "ATM mutations associated with impaired DNA repair function are also linked to an increased risk of gastric cancer, and are considered an independent prognosis factor in gastric cancer." (PMID 32206186, 2020). "Furthermore, in gastric cancer, low levels of ATM expression are associated with increased sensitivity to olaparib/paclitaxel combination therapy." (PMID 28751718, 2017). "Incidencies of ATM gene intron mutation in the gastric cancers (GC)." (PMID 24324828, 2013). "A possible association between germline ATM variants and an increased risk for gastric cancer had initially been suggested in genome-wide association studies (GWAS), as well as in reports of individual families with high gastric cancer rates segregating with an ATM variant." (PMID 37509701, 2023). "Moreover, ATM mutation and ATM protein loss included characteristics of old age, distal location of tumor, large tumor size, and histologic intestinal type in the human gastric cancer tissue." (PMID 30709340, 2019). "We have previously reported the ATM protein loss by immunohistochemistry (IHC) in 16% of human gastric cancer (GC) tissue." (PMID 24324828, 2013).
gastric cancer (continued). "In gastric cancer and hepatocellular carcinoma, the E3 ubiquitin ligase complex SCF promotes degradation of ARID1A, which is triggered by ATM activation due to DNA damage in gastric cancer and by mTORC1 activation in hepatocellular carcinoma." (PMID 39048965, 2024). "The high penetrance for gastric cancer in this family and the tendency towards early-onset malignancies in ATM carriers inferred from the literature support a possible role for gastric cancer surveillance, at least in cases with positive family histories." (PMID 37509701, 2023). "Despite the growing evidence, there are only few detailed clinical reports of families with ATM PVs displaying higher-than-expected gastric cancer occurrences." (PMID 37509701, 2023). "It is to be noted that while the occurrence of gastric cancer in the three siblings can be ascribed to the ATM PV, the possible contribution of environmental factors or other genetic variations cannot be excluded." (PMID 37509701, 2023). "Several studies subsequently reported the association between different types of tumors and PVs in the ATM gene, including gastric cancer." (PMID 37509701, 2023). "Similar to other cancer types, HRD somatic and germline mutations such as BRCA 1/2, PALB2, ATM, ARID1A and others have been found in around 10–15% of patients with gastric cancer." (PMID 37370858, 2023). "In the phase 3 GOLD study, the amount of ATM was confirmed by an ATM immunohistochemical (IHC) assay using formalin-fixed, paraffin-embedded gastric carcinoma tissues." (PMID 37215456, 2023). "ERBB2 and ATM levels both increases in liver cancer, stomach cancer and both decreases in kidney chromophobe cancer." (PMID 36056635, 2022). "In gastric cancer, ATM low protein expression subtype was exclusive with HER2 high protein expression." (PMID 36056635, 2022). "The role of multiple PARP inhibitors has also been evaluated in gastric cancer (GC) conditions as mutated homologous DNA recombination genes such as BRC1/2, PALB2, ATM, RAD51C, and ARID1A carry somatic HRD." (PMID 35873570, 2022). "Recent studies have shown that AZD6738, as a novel oral ATR inhibitor, can induce synthetic death of gastric cancer cells through ATM defect." (PMID 36035159, 2022). "Conversely, in five of these genes, all clonally mutated patients had mutations that were likely pathogenic (CTNNB1, ELF3, ATM, KMT2E, and PIK3CA), lending stronger support to their candidate gastric cancer driver status." (PMID 36970058, 2022). "Thereafter, we investigated how the mRNA levels of DNMT3A and ATM were correlated with the overall survival of gastric cancer patients." (PMID 34503060, 2021).